RNY3P9 (RNY3 pseudogene 9)
Gene: Miscellaneous RNA gene on chromosome 13 (40,226,827 to 40,226,932, forward strand). Ensembl gene ENSG00000207458.
Homologues: Orthologues: chimpanzee Y_RNA (93% identical), macaque Y_RNA (91% identical). Paralogues in human: RNY3 (85% identical), Y_RNA (85% identical), Y_RNA (84% identical), Y_RNA (83% identical), Y_RNA (82% identical), RNY3P1 (81% identical), Y_RNA (81% identical), Y_RNA (80% identical), RNY3P10 (79% identical), RNY3P16 (79% identical), RNY3P2 (79% identical), RNY3P3 (79% identical), and 91 more.